MITF (melanocyte inducing transcription factor)
Diseases named in the same sentence as MITF in open-access papers (continued):
Sharing a sentence is not in itself a finding about the gene and the disease.
melanoma (continued). "In general, a large body of evidence supports the view that increasing levels of MITF expression promote melanoma proliferation and drug resistance [extensively reviewed in Ref." (PMID 27896217, 2016). "To validate that increased DNA damage and cellular senescence in MiTF-silenced melanoma cells relied directly on the downregulation of the FANC pathway, we carried out experiments involving the forced expression of FANCA or FANCD2." (PMID 27827420, 2016). "MITF is the master regulator of melanoma cells, and it is responsible for controlling most of the important physiological cellular processes, such as proliferation, invasiveness, stemness, drug resistance and other functions." (PMID 27399772, 2016). "We show that MiTF downregulation in melanoma cells lowers the expression of several FANC genes and proteins." (PMID 27827420, 2016). "MITF's contribution to phenotypic heterogeneity and plasticity of melanoma is considered as an important part of reduced sensitivity to the BRAF/MEK/ERK pathway inhibition." (PMID 26824319, 2016). "A common mutation found in WS2 sufferers involves the microphthalmia-associated transcription factor (MITF), which plays a critical role in melanocytes and melanoma." (PMID 27349893, 2016). "Here the authors identify a lineage-specific requirement of the cytoplasmic polyadenylation binding protein 4 (CPEB4) in malignant melanoma and show that it controls melanoma drivers MITF and RAB27A." (PMID 27857118, 2016). "SKI thus helps to maintain the MITF homeostasis downstream of BRAFV600E required for BRAF-driven melanoma development." (PMID 26977879, 2016). "Our results suggested that Lebein induced inhibition in melanoma cellular proliferation that corresponded to MITF overexpression through decreases in ERK phosphorylation." (PMID 27399772, 2016). "SOX5 has a strong inhibitory effect on MITF expression and seems to have a decisive clinical impact on melanoma during tumor progression." (PMID 26927636, 2016). "There are other examples of drugs simultaneously reducing MITF and NF-κB activities in melanoma cells." (PMID 26824319, 2016). "Strikingly, we obtained very good prediction results (PCC r = 0.76) by using the optimization parameters of the SOX5/SOX10 model learned on the NCI-60 data for the prediction of MITF levels of the independent melanoma data set (33 melanoma samples)." (PMID 26927636, 2016). "The aim of this study was to further investigate the regulation of MITF and the impact of MITF regulators on melanoma progression." (PMID 26927636, 2016). "The microphthalmia-associated transcription factor (MITF) presents highly dynamic expression patterns in connection to proliferation and invasion in melanoma, with relevance for prognosis and therapy." (PMID 27535130, 2016). "The reduction of MITF expression has been reported as the result of the stimulation of melanoma cells with interleukin-1α or 1β suggesting that this process is NF-κB-dependent." (PMID 26824319, 2016). "While immunofluorescence (IF) analysis further confirmed the nuclear expression of MITF in TAFH RNAi-treated fibroblasts similar to melanoma cells." (PMID 27499390, 2016). "Essential in these CPEB4-controlled networks are the melanoma drivers MITF and RAB7A, a feature validated in clinical biopsies." (PMID 27857118, 2016). "MITF appears to be an important regulator of melanoma progression since the knock-down of its gene reduces proliferation and increases invasiveness." (PMID 27175588, 2016). "In line with our results, the co-overexpression of BCL-2 and β-catenin has been reported in other tumors and the transcriptional regulation of BCL-2 by MITF has been documented in primary melanocytes and melanoma cells." (PMID 27175588, 2016). "To conclusively understand the functional significance of induced MITF and the associated transcriptional program in AURKA-i-mediated anti-proliferative response, we tested melanoma cell viability in response to AURKA-i or si-MITF, or a combination thereof." (PMID 26962685, 2016).
melanoma (continued). "By focusing on melanomas during the initial response phase of treatment, we discovered that the upregulation of the melanoma survival oncogene MITF drives early drug tolerance." (PMID 26977879, 2016). "Specifically, less than 10% of exponentially growing melanoma cells displayed more than five 53BP1 foci per nucleus, a percentage that exceeded 60% when MiTF, FANCA or FANCD2 were silenced individually." (PMID 27827420, 2016). "In line with a crosstalk between MiTF and the FANC pathway, MiTF silencing in melanoma cells triggered a strong reduction in the mRNA level of 4 analysed FANC genes: FANCA, FANCD2, FANCC and FANCG." (PMID 27827420, 2016). "The forced expression of FANCA or FANCD2 in MiTF-depleted cells significantly reduced the occurrence of spontaneous DNA damage, as indicated by γH2AX and 53BP1 foci formation and foster melanoma cell proliferation in response to MMC exposure." (PMID 27827420, 2016). "Different MITF expression levels have been shown to result in very divergent clinical courses in melanoma patients." (PMID 26927636, 2016). "We reported many significant transcript isoform changes between breast tumors according to ER expression and between melanoma samples according to MITF expression." (PMID 27535130, 2016). "CPEB4 sgRNAs promoted a marked inhibition of MITF in pigmented melanoma cells with the consequent blockade of cell proliferation." (PMID 27857118, 2016). "Hoek and coworkers found that MITF levels can be used as a marker to distinguish proliferative and invasive phenotypes of melanoma cell lines with low MITF levels marking the invasive state." (PMID 26927636, 2016). "Although high MITF levels have an anti-proliferative effect, MITF expression is detectable in almost all melanoma tumors." (PMID 26927636, 2016). "To conclude, we applied a computational approach to infer transcriptional regulation of MITF in human melanoma cells employing microarray expression profiles." (PMID 26927636, 2016). "A strategy of melanoma cells to gain a high proliferation rate is to avoid high MITF expression levels, which have an anti-proliferative effect." (PMID 26927636, 2016). "We found a strong inverse correlation between the mRNA expression of ZEB1 and MITF in melanoma cell lines from the Cancer Cell Line Encyclopedia (CCLE), regardless of their BRAF/NRAS mutational status (n = 61, P = 4.08E‐11)." (PMID 27596438, 2016). "Taking these findings into consideration, we analyzed the crosstalk between EMT‐TFs and MITF in human melanoma cells." (PMID 27596438, 2016). "In the present report, MITF regulates transcription of Rab27a as a transcription factor in melanoma cells." (PMID 27381646, 2016). "By repositioning an HIV drug to target MITF as a driver of MAPK inhibitor (MAPKi)-induced drug tolerance we identify a clinically relevant approach for melanoma therapy that has the potential to improve initial responses and delay the onset of resistance." (PMID 26977879, 2016). "Numerous natural compounds have been reported to induce differentiation of melanoma cells through up regulation of MITF due to inhibition of ERK phosphorylation." (PMID 27399772, 2016). "We have reported previously that the microenvironment-driven suppression of the WNT/β-catenin pathway is accompanied by downregulation of MITF in MITFhigh patient-derived melanoma cell populations." (PMID 26824319, 2016). "The results of the present study indicate that making this kind of distinction using standard melanoma-associated markers would be very difficult because MM127 cells cannot be identified using S100, Melan-A, HMB-45, MITF or tyrosinase." (PMID 27087056, 2016). "Many genes involved in different cellular processes that are important for melanoma progression, such as proliferation, migration, invasiveness and senescence, are regulated by MITF, which has been proposed as the melanocytic lineage master regulator." (PMID 27399772, 2016).
melanoma (continued). "In MEK inhibitor‐resistant melanoma cells, MITF expression can be highly upregulated as a consequence of deregulated TGFβ signalling." (PMID 25818589, 2015). "Together our data identify BRG1 as an essential MITF cofactor in melanoma and melanocyte/melanoblast cells in vitro and in vivo." (PMID 25803486, 2015). "To better understand the molecular function of MITF, we used tandem affinity purification to isolate MITF from 501Mel melanoma cells and mass spectrometry to identify its interacting partners." (PMID 25803486, 2015). "MITF is a master regulator of melanocyte development and has been reported to be critical for melanoma progression." (PMID 25763355, 2015). "Despite its relevance for melanoma, the understanding of MITF as a target of phosphorylation is relatively limited and sometimes ambiguous." (PMID 25818589, 2015). "Most recent findings that modulation of MITF activity can drive phenotype switching in vivo, and abrogating MITF activity in melanoma leads to tumor regression, but a low level of wild-type MITF is oncogenic indicate that further studies are needed." (PMID 25433395, 2015). "ATF2 (activating transcription factor 2) displays inhibitory activity towards SOX10 both in melanocytes and melanoma cells, resulting in a decreased MITF transcript level." (PMID 25433395, 2015). "In this study, we further found that CM from hUCB-MSCs efficiently inhibited α-MSH-induced hyperpigmentation by reducing MITF activity in normal melanocytes and melanoma cell lines." (PMID 26024475, 2015). "In line with this, melanoma cell lines that lack MITF expression grow tumours less frequently and tumour onset is delayed by several months compared to MITF‐expressing cell lines." (PMID 25818589, 2015). "WNT5A-mediated downregulation of LEF-1 (a transcriptional regulator of MITF) switches the melanoma cell phenotype from proliferative to invasive." (PMID 26393652, 2015). "Despite MITF's essential function in melanoma cell proliferation, it also consistently regulates the expression of differentiation genes." (PMID 25818589, 2015). "Next, we dissected the role of the antagonistic MITF/c-Jun interrelationship for the kinetics of inflammation-induced dedifferentiation of melanoma cells." (PMID 26530832, 2015). "Whereas in these MITF‐negative cells, factors such as WNT5A and TGFβ appear to dominate the regulation of melanoma cell fate, in the MITF‐positive cells, MITF is the central regulator of melanoma cell survival, proliferation and differentiation." (PMID 25818589, 2015). "Over the last few years, the function of MITF has been tightly connected to plasticity of melanoma cells." (PMID 25433395, 2015). "The contribution of PAX3 (paired box 3) to MITF expression represents another melanoma-specific mechanism." (PMID 25433395, 2015). "p21Cip1, a cell cycle inhibitor, has been identified as a CREB co-factor involved in cAMP-dependent MITF expression in melanoma." (PMID 25433395, 2015). "Downregulation of MITF at the transcriptional level was observed for ciglitazone that also showed anti-melanoma effects in vivo." (PMID 25433395, 2015). "SWI/SNF can promote melanoma survival by remodeling the IAP promoter leading to enhanced MITF-driven BIRC7 (Livin/ML-IAP) expression." (PMID 26426052, 2015). "Melanomas with low levels of MITF are resistant to MAPK inhibitors and tend to exhibit high levels of NF-κB and AXL, while melanoma with high MITF levels exhibit low NF-κB activity and are more sensitive to MAPK inhibition." (PMID 26426052, 2015). "Expression of MITF has been used as a benchmark to distinguish melanoma cells in the proliferative or invasive state." (PMID 25763355, 2015). "Of note, conditional re-expression of MITF in HCmel3-R cell lines suppressed c-Jun and chemokine expression, corroborating that MITF directly counteracts the inflammatory cell state in murine melanomas as well." (PMID 26530832, 2015).
melanoma (continued). "MITF is recognized as a driver of melanoma progression [for review 6], but its role in suppression of invasion and metastasis has been also shown." (PMID 25433395, 2015). "While this clearly indicates that MITF expression is required for the maintenance of melanoma growth, transient MITF depletion enhances the metastatic potential of melanoma cells in a tail vein injection assay." (PMID 25818589, 2015). "Altogether, these findings support our model that an inflammatory melanoma cell state controlled by the antagonistic interrelationship between MITF and c-Jun fosters reciprocal interactions with myeloid immune cells." (PMID 26530832, 2015). "WNT5A expression is inversely correlated with MITF in proliferative and invasive melanoma phenotypes." (PMID 26393652, 2015). "In this context, MITF regulates oxidative metabolism and allows melanoma cells to adapt to local nutrient conditions." (PMID 25818589, 2015). "miR-211 was confirmed as being under transcriptional control of MITF following MITF induction in two melanoma cell lines (C-32 and HT144)." (PMID 25980496, 2015). "Recently, we have reported MITF as an essential regulator of microenvironment-driven alterations in melanoma phenotype." (PMID 26035829, 2015). "All dedifferentiated mouse melanoma cell lines (HCmel3-Rs and HCmel10) expressed low amounts of MITF and its targets, but high levels of c-Jun/Fosl1, showing that the MITFlow/c-Junhigh cell state is conserved in mouse melanomas." (PMID 26530832, 2015). "For example, exogenous MITF overexpression has been shown to repress the ability of BRaf inhibition to kill melanoma and in cells that display high MITF activity, class III and class IV melanosomes can sequester drugs." (PMID 26405815, 2015). "Next, we determined how MITF suppression changes the global responsiveness of human MZ7 melanoma cells (MITFhigh group) to increasing amounts of TNF-α." (PMID 26530832, 2015). "Aberrant miR-182 expression promotes melanoma metastasis by repressing FOXO3 and microphthalmia-associated transcription factor (MITF)." (PMID 26116372, 2015). "The consensus regarding why the cell invests such effort in maintaining control of MITF levels and why there are so many regulatory mechanisms, is that melanocytes and melanoma are exquisitely sensitive to even small variations in MITF expression." (PMID 25755924, 2015). "Our present study identified a reciprocal and antagonistic interrelationship between MITF and c-Jun as a molecular interface that orchestrates melanoma phenotype switching with inflammatory signals from the microenvironment." (PMID 26530832, 2015). "MITF's relevance for this cell lineage is maintained in melanoma, where it is an important regulator of survival and balances melanoma cell proliferation with terminal differentiation (pigmentation)." (PMID 25818589, 2015). "This variety of often mutually exclusive cellular programs driven by MITF stands for distinct phenotypes of melanoma cells [12, 20, 21; for review 22, 23]." (PMID 25433395, 2015). "We then examined the protein expression of these seven RTKs and MITF in a panel of 22 patient-derived melanoma cell lines by Western blot analysis." (PMID 25742786, 2015). "This theory was tested in an elegant in vivo study, in which a BRN2 reporter (GFP) and cellular pigmentation (as surrogate marker for MITF expression) were analysed during B16F2 melanoma progression." (PMID 25818589, 2015). "The majority of melanomas display great heterogeneity not only with regard to MITF‐negative and MITF‐positive populations, but also with regard to expression levels amongst the MITF‐positive cells." (PMID 25818589, 2015). "Because of its fundamental role in melanoma cells, the regulation of MITF's expression and function is extremely complex and dynamic." (PMID 25818589, 2015). "NURF acts downstream of MITF in melanocytes and melanoma cells co-regulating gene expression in vitro." (PMID 26440048, 2015).
melanoma (continued). "In contrast to β-catenin, a phenotype-specific expression of LEF1 has been shown in melanoma cells limiting LEF1/β-catenin-dependent MITF transcription to a defined cellular context." (PMID 25433395, 2015). "It has been proposed that melanoma invasion is triggered by the appearance of clusters of MITF-low/ZEB1-high cells at the edge of the primary lesions." (PMID 25865119, 2015). "It has been demonstrated in melanoma cells that MITF-derived C-terminal peptide cleaved by these proteases has a pro-apoptotic function." (PMID 25433395, 2015). "Nevertheless, this indicates that a third ‘class’ of melanoma cells exists where a particular intracellular signalling permits the co‐existence of MITF with AXL and WNT5A, which otherwise is mutual exclusive." (PMID 25818589, 2015). "Melanoma associated genes were indentified (via key words: melanoma, BRAF, and MITF) which produced a refined gene list (n = 16) common to all." (PMID 25980496, 2015). "MITF silencing in proliferative melanoma cells leads to cell cycle arrest and entry into senescence." (PMID 26440048, 2015). "As such, MITF has gained major recognition as a central player in melanoma development and has been assigned the role of a ‘lineage survival oncogene’." (PMID 25818589, 2015). "We have shown that MITF level and activity correlates well with the extent of heterogeneity of patient-derived melanoma cultures in EGF(+)bFGF(+) medium." (PMID 26035829, 2015). "MITF participates in executing diverse melanoma phenotypes defined by distinct gene expression profiles." (PMID 25433395, 2015). "As knockdown of MITF failed to block their growth we concluded that the residual levels of MITF were dispensable for the proliferation of these MITFlow cell lines, suggesting a stable epigenetically distinct and MITF-independent melanoma cell state." (PMID 26530832, 2015). "This regulation has gained relevance in the context of microenvironment signalling from immune cells, where macrophage‐derived TNF‐α appears to be required for the maintenance of MITF expression during melanoma growth." (PMID 25818589, 2015). "What has been shown is that S73 phosphorylation is required for its interaction with the acetyltransferase p300 in human melanoma cells carrying a BRAF mutation, an observation that suggests a role of MAPK signalling in MITF acetylation." (PMID 25818589, 2015). "Then, gene expression profiles of MITF knockdown melanoma cells and control melanoma cells were also evaluated." (PMID 26207740, 2015). "An unphosphorylatable mutant at Ser73/Ser409 has been very stable but transcriptionally incompetent, indicating that signals promoting transcriptional activity and degradation of MITF protein are coupled in melanoma cells." (PMID 25433395, 2015). "Acetylation and also ubiquitination have been linked to ERK/MAPK signalling, which provides a direct link of MITF abundance and function with the most predominantly deregulated pathway in melanoma." (PMID 25818589, 2015). "Due to the multifactorial and dynamic nature of MITF regulation, it often varies amongst individual melanoma cells with regard to the levels of MITF expression." (PMID 25818589, 2015). "The 3′-UTR of MITF transcript is also targeted by miR-148, miR-101 and miR-218, and inverse correlation between MITF and miR-218 has been observed in melanocytes and melanoma cell lines." (PMID 25433395, 2015). "TFAP2A is a TF involved in melanoma and normal melanocyte function and co-localizes with MITF at promoters involved in pigment cell differentiation in primary human melanocytes (H Seberg, E van Otterloo, and RA Cornell, manuscript in preparation)." (PMID 25803486, 2015). "Melanoma is a melanocyte-derived tumor in which MITF dependence is retained [for review 3]; thus, MITF represents a lineage-restricted regulator that operates in normal cells, and its activity is also used by malignant cells." (PMID 25433395, 2015).